PALS1 (protein associated with LIN7 1, MAGUK p55 family member)
Description:
Plays a role in tight junction biogenesis and in the establishment of cell polarity in epithelial cells. Also involved in adherens junction biogenesis by ensuring correct localization of the exocyst complex protein EXOC4/SEC8 which allows trafficking of adherens junction structural component CDH1 to the cell surface (By similarity). Plays a role through its interaction with CDH5 in vascular lumen formation and endothelial membrane polarity. Required during embryonic and postnatal retinal development (By similarity). Required for the maintenance of cerebellar progenitor cells in an undifferentiated proliferative state, preventing premature differentiation, and is required for cerebellar histogenesis, fissure formation, cerebellar layer organization and cortical development (By similarity). Plays a role in neuronal progenitor cell survival, potentially via promotion of mTOR signaling (By similarity). Plays a role in the radial and longitudinal extension of the myelin sheath in Schwann cells (By similarity). May modulate SC6A1/GAT1-mediated GABA uptake by stabilizing the transporter (By similarity). Plays a role in the T-cell receptor-mediated activation of NF-kappa-B. Required for localization of EZR to the apical membrane of parietal cells and may play a role in the dynamic remodeling of the apical cytoskeleton (By similarity). Required for the normal polarized localization of the vesicular marker STX4 (By similarity). Required for the correct trafficking of the myelin proteins PMP22 and MAG (By similarity). Involved in promoting phosphorylation and cytoplasmic retention of transcriptional coactivators YAP1 and WWTR1/TAZ which leads to suppression of TGFB1-dependent transcription of target genes such as CCN2/CTGF, SERPINE1/PAI1, SNAI1/SNAIL1 and SMAD7 (By similarity). (Microbial infection) Acts as an interaction partner for human coronaviruses SARS-CoV and, probably, SARS-CoV-2 envelope protein E which results in delayed formation of tight junctions and disregulation of cell polarity.
Synonyms: MPP5; FLJ12615
Tractability: Small molecule: a structure with a bound ligand is known. Antibody: UniProt places it where antibodies can reach, with high confidence; its Gene Ontology location is reachable by antibodies, with high confidence. PROTAC: ubiquitination databases record sites on it.
Gene: Protein-coding gene on chromosome 14 (67,240,713 to 67,336,061, forward strand). Ensembl gene ENSG00000072415.
Subcellular location: Golgi apparatus; Cell membrane; Endomembrane system; Cell junction, tight junction; Cell junction, adherens junction; Cell projection, axon; Perikaryon; Apical cell membrane; Endoplasmic reticulum-Golgi intermediate compartment
Subcellular location (Human Protein Atlas): Nucleoplasm; Plasma membrane; Cell Junctions; Cytosol
Pathways (Reactome):
Disease: SARS-CoV-1 targets PDZ proteins in cell-cell junction; SARS-CoV-2 targets PDZ proteins in cell-cell junction
Cell-Cell communication: Tight junction interactions
Gene Ontology:
Molecular function: identical protein binding; protein binding; protein domain specific binding
Biological process: morphogenesis of an epithelial sheet; central nervous system neuron development; cerebral cortex development; establishment or maintenance of epithelial cell apical/basal polarity; establishment or maintenance of polarity of embryonic epithelium; generation of neurons; protein localization to plasma membrane; regulation of transforming growth factor beta receptor signaling pathway; myelin assembly; peripheral nervous system myelin maintenance; protein localization to myelin sheath abaxonal region
Cellular component: adherens junction; apical plasma membrane; cell junction; cytoplasm; endoplasmic reticulum-Golgi intermediate compartment; extracellular exosome; Golgi apparatus; plasma membrane; protein-containing complex; apical junction complex; endoplasmic reticulum-Golgi intermediate compartment membrane; perikaryon; apical part of cell; axon; bicellular tight junction; endomembrane system; lateral loop; myelin sheath adaxonal region; Schmidt-Lanterman incisure
Genetic constraint (gnomAD): Loss-of-function variants: 26 observed, 55.78 expected, observed/expected ratio (o/e) 0.47, 90% interval 0.34 to 0.65. The upper end of that interval is the gene's LOEUF score, 0.65, which puts it in group 2 of 6, group 1 being the genes least tolerant of losing a copy. Missense variants: 576 observed, 696.15 expected, observed/expected ratio (o/e) 0.83, 90% interval 0.77 to 0.89. Synonymous variants: 224 observed, 226.68 expected, observed/expected ratio (o/e) 0.99, 90% interval 0.88 to 1.1.
Homologues: Orthologues: chimpanzee PALS1 (100% identical), pig PALS1 (99% identical), macaque PALS1 (98% identical), guinea pig PALS1 (98% identical), rat Pals1 (97% identical), mouse Pals1 (97% identical), dog PALS1 (93% identical), rabbit PALS1 (91% identical), tropical clawed frog pals1 (87% identical), zebrafish pals1a (77% identical), zebrafish pals1b (52% identical), Drosophila melanogaster sdt (48% identical), and 1 more. Paralogues in human: MPP7 (33% identical), MPP3 (30% identical), MPP4 (29% identical), PALS2 (27% identical), MPP2 (27% identical), CASK (23% identical), MPP1 (18% identical).
Diseases named in the same sentence as PALS1 in open-access papers:
PALS1 is named in the same sentence as 39 diseases in open-access papers, as found by Europe PMC text mining. Sharing a sentence is not in itself a finding about the gene and the disease. The quoted sentences say what the papers report.
colorectal cancer (3 papers, 2021 to 2025). A primary or metastatic malignant neoplasm that affects the colon or rectum. "Loss of Pals1 in colorectal cancer cells results in increased Arf6 and Rac1 activity, enhanced cell migration and invasion in vitro and increased metastasis of transplanted tumor cells in mice." (PMID 33941200, 2021). "To elucidate whether our findings regarding the effects of Pals1 loss are valid for other colorectal cancer cell lines, we established a Pals1 knockout in another cell line, Caco-2." (PMID 36494580, 2023). "Taken together, we identified a redundancy between SMAP1 and Pals1 in the regulation of activation of Arf6/Rac1, thereby controlling cell migration, invasion, and metastasis of colorectal cancer cells." (PMID 36494580, 2023). "We have recently shown that downregulation of the tight junction adapter protein Pals1 in colorectal cancer cells results in an increase of cell migration, invasion, and metastasis due to the enhanced activation of Arf6 and Rac1." (PMID 36494580, 2023). "Recently, we revealed a new function of the polarity regulator Pals1 in controlling cell motility of colorectal cancer cells by inhibiting Arf6, which in its turn controls Rac1-dependent lamellipodia formation and tumor cell migration/invasion." (PMID 36494580, 2023). "In a parallel approach, we tested another SMAP1-deficient colorectal cancer cell line, SW48 and observed indeed a similar behavior as with HCT116 cells: Deletion of Pals1 further reduced the cortical TJ marker ZO1 and displaced PATJ and Crb3a from the junctions." (PMID 36494580, 2023). "In a previous study, we showed that Pals1 binds and inhibits Arf6 in colorectal cancer cells." (PMID 36494580, 2023). "Thus, our data reveal a new function of Pals1 as a key inhibitor of cell migration and metastasis of colorectal cancer cells." (PMID 33941200, 2021). "Moreover, inhibition of Arf6 reduces cell migration of Pals1/SMAP1-double deficient cancer cells and might be considered as a future therapeutic approach for a subset of colorectal cancer patients." (PMID 36494580, 2023). "Finally, evaluation of mRNA expression of colorectal cancer specimen (TCGA project) revealed a poorer survival prognosis of patients suffering from colorectal cancer if tumor samples display low Pals1 and SMAP1 expression in contrast to tumors with either Pals1 or SMAP1 downregulation." (PMID 36494580, 2023). "Taken together, we concluded from these experiments that Pals1 functions in redundancy with SMAP1 to control the levels of active Arf6 and thus Rac1-mediated cell migration in colorectal cancer cells." (PMID 36494580, 2023). "One possibility to explain the different migration behavior of HCT116 and other colorectal cancer cell lines would be that in HCT116 cells, Arf6 is more sensitive towards the regulatory function of Pals1." (PMID 36494580, 2023). "Notably, deletion of Pals1 in three other colorectal cancer cell lines (Caco-2, DLD1 and RKO) alone does not increase cell migration or Arf6/Rac1 activity, due to the expression of the Arf6-specific GAP SMAP1." (PMID 36494580, 2023). "However, we now found that deletion of Pals1 in other colorectal cancer cell lines did not result in enhanced Arf6/Rac1-dependent cell migration." (PMID 36494580, 2023).
cyst (3 papers, 2018 to 2024). A sac-like closed membranous structure that may be empty or contain fluid or amorphous material. "So far, analyzed SLCs keep their nephron-segment specific expression and distribution in Pals1-depleted kidneys, even in cyst lining epithelia." (PMID 35252349, 2022). "As the knockdown of Pals1 in the whole mouse nephron led to cyst formation and Hippo pathway inactivation, we hypothesized that the integrity of tight junctions is a crucial factor in the control of Hippo signaling." (PMID 30154411, 2018). "Thus, in case that transport activities of a group, or a single SLC family member significantly aggravate cyst formation, downregulation of SLCs in Pals1-depleted renal epithelia could be part of a protective “rescue” effect, preventing further (or faster) progression of the phenotype." (PMID 35252349, 2022). "In MDCK II cells, a model for cell polarization, depletion of PALS1 - which binds to all CRB components - leads to defective cell polarization and improper distribution of tight junction proteins, resulting in severe epithelial barrier defects in 3D cyst models." (PMID 39614182, 2024). "This study investigated whether this phenotype is associated with transcriptional changes by analyzing wildtype (WT) and PALS1 knockout (KO) MDCK II cell lines grown under non-confluent conditions and in 3D cyst cultures." (PMID 39614182, 2024).
Renal cyst (3 papers, 2022 to 2024). A fluid filled sac in the kidney. "Mice that are functionally haploid for Pals1 develop a lethal phenotype, accompanied by heavy proteinuria and the formation of renal cysts." (PMID 35252349, 2022). "Mice with nephron-specific Pals1 haploinsufficiency suffered from renal cyst formation and severe defects in renal barrier function, indicative of abnormal SDs, resulting in early death (6–8 weeks)." (PMID 35265622, 2022). "In a study using Pals1-haploinsufficient mice, in which Pals1 is involved in renal cell polarity in the juxta-membrane domain, a lethal phenotype developed, accompanied by heavy proteinuria and renal cyst formation." (PMID 39125325, 2024).
microcephaly (2 papers, 2020 to 2023). A congenital or acquired developmental disorder in which the circumference of the head is smaller than normal for the person's age and sex. "Here, our studies of Pals1, a human microcephaly-causing gene, show that an entosis-like process (hereafter referred to as entosis) results in engulfed cells that are visible within dividing cortical progenitors." (PMID 36604424, 2023). "It has been shown previously that Pals1 mutation causes microcephaly in humans and that its cortex-specific deletion generates mice lacking a cortex due to massive cell death." (PMID 36604424, 2023). "We find that mice mutant for the human microcephaly-causing gene Pals1, which exhibit diminished cortices due to massive cell death, also exhibit nuclei enveloped by plasma membranes inside of dividing cells." (PMID 36604424, 2023). "Next, because a high proportion of mitotic cells include CIC structures, we examined the cellular consequences of persistent entotic cells and how they contribute to the pathology of microcephaly in Pals1 mutants." (PMID 36604424, 2023). "It is possible that only Pals1 mutants offer this rare combination that results in distinct microcephaly." (PMID 36604424, 2023).
retinal degeneration (2 papers, 2019 to 2022). Degeneration of the retina. "Crb1, MPP4, PALS1, and aPKC, located in the AJs, are reported to be essential for photoreceptor morphogenesis and retinal degeneration." (PMID 36429029, 2022). "Ablation of PALS1 in the mouse neural retina resulted in late onset retinal degeneration suggestion redundancy of MPPs in the neural retina, whereas ablation of PALS1 in the mouse RPE and neural retina results in early onset retinal degeneration suggesting specific roles for PALS1 in RPE." (PMID 31795518, 2019).
bladder pain syndrome (1 paper, 2014). "Thus miR-199a-5p is expressed in the bladder's smooth muscle and urothelium and may play a role in bladder pain syndrome by suppressing LIN7C, ARHGAP12, PALS1, RND1 and PVRL1." (PMID 24574962, 2014).
ciliopathies (1 paper, 2024). "Furthermore, the ORAs also matched several signaling pathways, including WNT-, Hippo-, Hedgehog, and mTOR signaling which have not only been linked to ciliogenesis and/or ciliopathies before, but also directly to PALS1." (PMID 39614182, 2024).
COVID-19 (1 paper, 2022). A disease caused by infection with severe acute respiratory syndrome coronavirus 2. "Using the number of bonds formed between the E peptide and PALS1 PDZ domain as a measure of stability, this could potentially explain why SARS-CoV-1 was less severe than MERS and COVID-19 and why COVID-19 appears to be more severe than both MERS and SARS diseases were." (PMID 36016329, 2022).
Hydrocephalus (1 paper, 2017). Hydrocephalus is an active distension of the ventricular system of the brain resulting from inadequate passage of CSF from its point of production within the cerebral ventricles to its point of absorption into the systemic circulation. "Mpdz is associated with components of the planar cell polarity complex via binding to Pals1, and disturbance of planar cell polarity can lead to hydrocephalus in mouse models." (PMID 28500065, 2017).
influenza (1 paper, 2022). An acute viral infection of the respiratory tract, occurring in isolated cases, in epidemics, or in pandemics; it is caused by serologically different strains of viruses (influenzaviruses) designated A, B, and C, has a 3-day incubation period, and usually lasts for 3 to 10 days. "Notably, ZO-1 and PALS1 are targeted by other viruses, such as influenza and SARS-CoV, to disrupt and open TJs to efficiently exit the airway epithelia to spread and disseminate." (PMID 35283834, 2022).
SARS-CoV infection (1 paper, 2014). "In this work a human lung cDNA library was chosen to further mimic SARS-CoV infection, whereas PALS1 was identified using a human placenta cDNA collection." (PMID 25122212, 2014).
tumor (10 papers, 2018 to 2025). "We find that as in tumor cells, this entosis produces dynamic and mobile cellular entities that are highly associated with lengthened mitosis, chromosomal defects, and abnormal cytokinesis in Pals1 mutants." (PMID 36604424, 2023). "ZEB1 owes its pivotal role to the downregulation of E-cadherin and the regulation of further proteins involved in tumor progression, such as Crumbs3, HUGL2, and PATJ (Pals1-associated tight junction)." (PMID 34884646, 2021). "In the next step we analysed whether CLDN3, PALS1 and PAR6 expression levels were associated with tumor grade." (PMID 34531452, 2021). "Finally, we checked whether the proposed mechanism of Pals1 controlling tumor cell migration/metastasis in redundancy with SMAP1 is also reflected in patient cohorts." (PMID 36494580, 2023).
cancer (7 papers, 2021 to 2025). A tumor composed of atypical neoplastic, often pleomorphic cells that invade other tissues. "Remarkably, entosis in the Pals1 mutants shares important features with entosis found in cancer cell lines." (PMID 36604424, 2023). "We further found that Pals1 prevents cancer cell metastasis by controlling Rac1-dependent cell migration through inhibition of Arf6, which is independent of the canonical binding partners of Pals1." (PMID 33941200, 2021). "It is unknown whether entosis in Pals1 mutants is identical to typical entosis found in cancer cells in which live cells are engulfed by host cells." (PMID 36604424, 2023).
infection (5 papers, 2018 to 2024). The state of being infected such as from the introduction of a foreign agent such as serum, vaccine, antigenic substance or organism. "The DLLV motif within the C-terminal domain binds to tight junction-associated protein (PALS1) to ease the way for infection." (PMID 34220784, 2021). "The 68th amino acid position we highlight in this study is in the c-terminal domain, which coincides with the previously reported motif in SARS-CoV-1 (also at 68th amino acid position) that binds to the host cell PALS1 protein to facilitate infection." (PMID 33396801, 2020). "It is known that GS infection delocalizes the tight junctions claudin-1 and occludin in polarized Caco-2 cells but herein, we further show effects on amot (scaffolding protein) and mpp5 (PDZ protein that binds tight junction proteins, also known as Pals1)." (PMID 30062089, 2018).
PALS1 also shares sentences with these, for which no sentence is quoted: bladder cancer (2 papers); breast carcinoma (2); hepatocellular carcinoma (2); liver cancer (2); adult-onset Still disease (1); autism (1); cervical cancer (1); colon tumor (1); developmental delays (1); epilepsy (1); hepatoblastoma (1); Hypertension (1); keratosis (1); kidney disease (1); lung carcinoma (1); mental disorder (1); metabolic disorder (1); personality disorder (1); preeclampsia (1); prostate carcinoma (1); pulmonary disorder (1); renal carcinoma (1); Retinal dysplasia (1); retinitis pigmentosa (1); schizophrenia (1).